NANOG (Nanog homeobox)
Diseases named in the same sentence as NANOG in open-access papers (continued):
Sharing a sentence is not in itself a finding about the gene and the disease.
breast carcinoma (continued). "Specifically, the expression of NANOG and SOX2, which are demonstrated to drive tumorigenesis and metastasis in breast cancer, was 5-fold higher in CD44−/low/CD24−/low cells from luminal cell lines compared to CD44high/CD24−/low cells from Hs578T." (PMID 32423137, 2020). "Human tissues for positive controls showed the expected staining patterns: for OCT4 and NANOG on seminoma, SOX2 on skin, KLF4 on breast carcinoma, and c-MYC on colon." (PMID 32850316, 2020). "ALKBH5 belongs to the non-heme Fe(ii)- and α-ketoglutarate (KG)-dependent dioxygenase AlkB family of proteins demethylated NANOG mRNA, and stimulated the expressions of HIF-1α and HIF-2α of breast cancer cells when exposure to hypoxia." (PMID 32500031, 2020). "Expected staining patterns were demonstrated in the human positive control tissues: seminoma for OCT4 and NANOG, normal skin for SOX2, breast carcinoma for KLF4, and normal colon for c-MYC." (PMID 32019273, 2020). "Positive controls demonstrated the expected staining pattern for OCT4 and NANOG in seminoma, SOX2 in normal skin, KLF4 in breast carcinoma, and c-MYC in normal colon." (PMID 32019273, 2020). "Using human breast cancer datasets, this study further found that TNBC patients with higher levels of Cx26/FAK/NANOG had decreased relapse-free survival compared to those with lower expression." (PMID 32514188, 2020). "The correlation of expression of leptin receptor (OBR), leptin-targeted genes (CDK8, NANOG, and RBP-Jk), and breast cancer (BC) patient survival was determined from The Cancer Genome Atlas (TCGA) mRNA data." (PMID 32471192, 2020). "Human tissues used for positive controls demonstrated positive staining of OCT4 and NANOG on sections of seminoma, SOX2 on skin, KLF4 on breast carcinoma, and c-MYC on colon." (PMID 32850316, 2020). "It was reported that hypoxia induces the breast cancer stem cell phenotype by HIF-dependent and ALKBH5-mediated m6A-demethylation of NANOG mRNA." (PMID 33489865, 2020). "The gene c-myc is over-expressed in breast cancer and SOX2 and NANOG are critical regulators of self-renewal, as well as pluripotency of embryonic stem cells, and are CSC markers." (PMID 33375053, 2020). "Recently, binding sites for OCT4, NANOG, SOX2 and SIN3A in breast cancer CTC clusters were shown to be hypomethylated to what is seen in embryonic stem cell biology." (PMID 30875950, 2019). "This was accompanied by an increase in breast cancer stemness (SOX2, OCT4, and NANOG levels) and significant increase in the levels of key drug transporters (ABCG2, ABCB1, and ABCC1)." (PMID 31867270, 2019). "In hypoxic breast cancer cells, ALKBH5 demethylates NANOG mRNA and elevates the protein level via reduced mRNA decay, on the premise of hypoxia-inducible factors (HIFs)." (PMID 31921664, 2019). "Expression of VIM, CDH1, CDH2, PLS3, CXCR4, CD44 and NANOG have been found in healthy controls and the maximal expression levels of these genes were the threshold beyond which CTCs-EBF of breast cancer patients were considered positive." (PMID 30634453, 2019). "In breast cancer, hypoxia facilitates expression of ALKBH5, resulting in reduction of NANOG mRNA m6A level and enhancement of mRNA stabilization." (PMID 31801551, 2019). "Pyrvinium pamoate, an anthelmintic drug and inhibitor of the Wnt/β-catenin pathway, prevented the proliferation of breast cancer cells, especially CD44+CD24−/low and ALDH+ CSCs, via downregulating NANOG, OCT4, and SOX2." (PMID 31137841, 2019). "In breast cancer, ALKBH5 mediated the m6A-demethylation of NANOG mRNA, thereby inducing the breast cancer stem cell phenotype." (PMID 30987661, 2019). "In their study, they showed that ALKBH5 increased NANOG expression level by demethylating NANOG mRNA in the 3’UTR, promoting breast cancer stem cell renewal." (PMID 30922314, 2019).
breast carcinoma (continued). "HIF-1 was required for the activation of the p38 MAP kinase pathway and inhibition of ERK signaling resulting in stabilization of NANOG, KLF4, and enrichment of breast cancer stem cells." (PMID 30301213, 2018). "The same group showed further that both ALKBH5 and ZNF217 participate in the hypoxia-induced NANOG and KLF4 (another pluripotency factor gene) overexpression in breast cancer cells." (PMID 29686311, 2018). "Similar to hypoxia exposure, overexpression of ALKBH5 not only decreases NANOG mRNA methylation, but also increases NANOG (Nanog homeobox) levels, resulting in elevation of the CSC population in breast cancer." (PMID 29439529, 2018). "Our findings show that both molecules increase epithelial to mesenchymal transition and migratory capacity of breast cancer cells, as well as cancer stem cell numbers, by increasing the expression of pluripotency genes such as ALDH1A1, KLF4, and NANOG." (PMID 30131941, 2018). "Exposure of breast cancer cells to hypoxia promotes the ALKBH5-mediated demethylation of m6A in NANOG transcripts, consequently enhancing NANOG expression." (PMID 29439529, 2018). "Here, the authors show that connexin 26 (Cx26) regulates the self-renewal of breast cancer stem cells via a ternary complex with FAK and NANOG." (PMID 29422613, 2018). "Consistently, H19 expression was detected at higher levels in breast cancer cells than in breast epithelial cells and stemness-related factors OCT4, SOX2 and NANOG were expressed at higher levels in MDA-MB-231 cells compared with MCF-10A cells." (PMID 28102845, 2017). "In recent studies, we found that hypoxia-inducible factors (HIFs) mediated increased NANOG, SOX2, and OCT4 expression in human breast cancer cells in response to chemotherapy or hypoxia." (PMID 27590511, 2016). "We previously demonstrated that hypoxia-induced m6A demethylation of NANOG mRNA by ALKBH5 positively regulated NANOG expression and the BCSC phenotype in MCF-7 and MDA-MB-231 breast cancer cells." (PMID 27590511, 2016). "This novel finding in MDBMSCC is consistent with previous studies reporting on cytoplasmic expression of NANOG in cervical cancer and SALL4 in breast cancer cells, inferring cytoplasmic expression as a predictor of poor prognosis." (PMID 27532037, 2016). "A more pronounced effect of MUC16-Cter is observed in LMO2 expression compared to NANOG in T3M4 and Jak2+/+ mammary tumor cells." (PMID 25691062, 2015). "In the present study, we analyzed the expression profiles of the same panel of stemness genes belonging to the OCT3/SOX2/NANOG/KLF4 core circuitry and acting in regulating stem cell biologyin a representative sample of primary breast cancer tissue." (PMID 25127259, 2014). "NANOG has also been identified in breast cancer cells and was found to mediate multidrug resistance via activation of STAT3 signaling suggesting that NANOG is a potential target for breast cancer therapeutics." (PMID 23662114, 2013). "Human embryonic stem cell genes NANOG, GDF3 and STELLA, which are downregulated when cells commit differentiation, are expressed in TGCT and in breast cancers." (PMID 17040570, 2006). "In MDA-MB-231 cells, GATAD2B knockdown significantly reduced expression of cancer stem-like cells factors OCT4, SOX2, c-Myc and NANOG, at both protein and mRNA level, further implicating the role of GATAD2B in maintaining cancer stem-like cells phenotype in breast cancer cells." (PMID 40136647, 2025). "Recent research in breast cancer has revealed that clusters of circulating tumour cells (CTCs) with metastatic potential exhibit hypomethylation of stemness-related transcription factors, including SOX2, NANOG, OCT4, and SIN3A." (PMID 38920995, 2024). "The increased expression of HIF-1 dependent S100A10 can form complexes and interact with histone demethylase KDM6A, ultimately being recruited to the OCT4 binding site to erase H3K27 trimethylation chromatin markers and promote transcription of NANOG, SOX2 and KLF4 in breast cancer." (PMID 38561775, 2024).
breast carcinoma (continued). "Further bioinformatics analysis of breast cancer based on TCGA database and the in vitro and in vivo detection results showed that TSP50 can regulate the expression of key BCSC factors, such as CD44, ALDH1, NANOG and OCT4." (PMID 39030572, 2024). "Hypoxia, through hypoxia-inducible factor (HIF), is known to induce a human Embryonic SC (hESC)-like transcriptional program, including the induced pluripotent stem cell (iPSC) inducers OCT4, NANOG, SOX2, KLF4, and cMYC, in various cancer cell lines, including breast cancer." (PMID 36982940, 2023). "In this relation, our Kaplan-Meier analyses revealed that NACT-treated breast cancer patients with elevated OCT4 and NANOG have significantly lower RFS (OCT4, p < 0.05; NANOG, p < 0.01) (Online Resource 4) in comparison to patients furnishing lower levels of OCT4 and NANOG." (PMID 38038865, 2023). "In addition, the inhibition of ZNF217-dependent m6A methylation of NANOG and KLF4 mRNA was found to be enhanced in breast cancer cells under hypoxia, thus promoting the occurrence and development of breast cancer." (PMID 35251177, 2022). "Similarly in breast cancer, Hh signaling can be enhanced via expression of tetraspanin 8 and LncRNA-Hh, which increases the expression of OCT4, SOX2, and NANOG and leads to enhanced self-renewal and oncogenicity 50,51." (PMID 36118530, 2022). "Similarly in breast cancer, the NF-κB pathway regulates the expression of OCT4, SOX2, and NANOG via upregulation of components of the NF-κB signaling pathway, including NIK 56,57." (PMID 36118530, 2022). "In breast cancer, PD-L1 helps maintain a stemness phenotype in MICs in vitro and in a mouse xenograft model via PI3K/AKT signaling that leads to phosphorylation of OCT4 and subsequent regulation of OCT4 and NANOG expression." (PMID 36118530, 2022). "Indeed, ALKBH5 overexpression decreases m6A methylation of NANOG mRNA at 3′ untranslated region (3′UTR), increasing NANOG mRNA stability and levels, and induces BCSC enrichment in hypoxic breast cancer cells." (PMID 35063010, 2022). "Furthermore, the expression of NANOG, OCT3/4, SOX2 by CTCs in breast cancer is directly related to disease progression." (PMID 35820816, 2022). "Hence, we propose that a dual reporter including one of the pluripotency markers (phOCT4-EGFP/NANOG-GFP/SORE6-GFP/SOX2 SRR2-pGreen fire) and ALDH1A1-DsRed2 can efficiently mark all the heterogeneous CSCs, at least in breast cancer." (PMID 34150761, 2021). "In normal epithelial or luminal breast cancer cells, FAK and NANOG did not bind each other but did associate with Cx26." (PMID 32514188, 2020). "Furthermore, the report found that loss of EphA5 resulted in higher expression of cancer stem cell (CSC) markers in HER2-positive breast cancer cells, including CD44+/CD24-/low, NANOG, CD133+." (PMID 31956298, 2020). "ALKBH5 suppresses NANOG and KLF4 degradation, which promotes breast cancer progression." (PMID 32021563, 2020). "The translation of a subset of the mRNA isoforms of NANOG, SNAIL, and NODAL promoted breast cancer cell plasticity in response to hypoxia, mTOR inhibition and chemotherapy by allowing efficient translation and escape from stress-induced translational repression." (PMID 32427827, 2020).
breast carcinoma (continued). "ALKBH5 promoted breast cancer stem cell (BCSC) specification and enrichment in the tumor microenvironment though catalyzing the demethylation of an adenosine residue in the 3′-UTR of NANOG mRNA." (PMID 32742194, 2020). "NANOG contributes to carcinogenesis via activating and preserving CSCs properties by regulating some genes or pathways, such as Stat3/Snail EMT, in many carcinomas, including breast cancer." (PMID 33375053, 2020). "In breast cancer, hypoxia elevated the expression of ALKBH5, and then, demethylated NANOG mRNA." (PMID 30987661, 2019). "Furthermore, genetic ablation of eIF4A in TNBC cells resulted in a decrease in breast cancer stemness (reduced expression of SOX2, OCT4, and NANOG levels) mirroring the level of eIF4A." (PMID 31867270, 2019). "In breast cancer stem cells (BCSCs), ZNF217 has been reported to interact with METTL3 and inhibit the m6A methylation of KLF4 and NANOG, which ultimately leads to high expression of KLF4 and NANOG, thus promoting tumorigenesis." (PMID 30031372, 2018). "NANOG cooperates with STAT3 to maintain pluripotency and self-renewing cells, after down-regulation of NANOG, cell proliferation, colony formation, and migration are reduced in breast cancer cells." (PMID 30542507, 2018). "To understand potential links between aging and breast cancer stemness, we employed the GenAge Human Genes list to screen for genes that are correlated with core stemness factor OCT4, SOX2, NANOG, and KLF4 in a cohort of breast cancer cell lines collected from the TCGA database." (PMID 30038266, 2018). "Normal positive staining patterns for OCT4 (brown), NANOG (purple), SOX2 (brown), c-Myc (brown), and KLF4 (purple) were demonstrated on human seminoma, normal skin, breast cancer, and prostate tissues, respectively." (PMID 29404335, 2017). "As for the minimal change in expression of SOX2, OCT4, and NANOG following therapeutic treatment in the MCF7 cells, this may be due to MCF7 being a luminal breast cancer subtype." (PMID 28871147, 2017). "Similarly, small RNA interference technology against NANOG reduced cell proliferation, migration and colony formation of MCF7 and MDA-MB-231 breast cancer cells." (PMID 26580604, 2015). "We observed a 10-fold decrease in NANOG protein levels in the GSI-treated cells, suggesting that NANOG may be NOTCH1-regulated in mouse and human breast cancer cells." (PMID 22992387, 2012). "The exact mechanism behind Shh maintaining the CSC self-renewal capabilities is unknown; however, studies performed on thyroid cancer, embryonal RMS, and breast cancer revealed that increased Shh and SMO signalling lead to increased expression of SOX2, NANOG, OCT3/4, and KLF4 transcription factors." (PMID 38920995, 2024). "Exploration of the mechanism revealed that when matrix stiffness was increased, TAZ dissociated from NANOG, promoting the transcription of SOX2 and OCT4, which in turn increased the proportion of BCSCs in the breast cancer and promoted the stemness phenotype of breast cancer." (PMID 37916166, 2023). "Furthermore, ZNF217, an m6A methyl-transferase inhibitor, inhibits the m6A modification of several pluripotency factor mRNAs, including NANOG, KLF4 and SOX2 in breast cancer to promote the CSC-like phenotype and breast cancer metastasis under hypoxic conditions." (PMID 34831207, 2021). "It was previously shown in breast cancer stem cells that decreased G-protein-coupled receptor 3, of which CBD is an inverse agonist, increased the expression of NANOG, which could explain the increase in NANOG in response to CBD." (PMID 34832951, 2021). "We should mention that OCT4, NANOG, and SOX2 could also explain the effect of ZFHX3 on BCSC features as they are known stem cell factors, and their expression was also upregulated by ZFHX3 in breast cancer cells." (PMID 33217982, 2020).
breast carcinoma (continued). "ALKBH5 demethylates m6A marks from NANOG, a master pluripotency factor; the oxidative demethylation activity of the ALKBH5 increases the NANOG transcript and protein expression that enriches breast cancer stem cells in the reduced oxygen tumor microenvironment promoting cancer progression." (PMID 33511112, 2020). "In breast cancer, Zhang and colleagues proposed that the exposure of breast cancer cells to hypoxia could stimulate hypoxia-inducible factor (HIF)-1α- and HIF-2α-dependent expression of ALKBH5, which induced m6A demethylation and stabilization of NANOG mRNA." (PMID 29587823, 2018). "We confirmed that Cx26, NANOG, and FAK proteins were expressed at similar levels in all analyzed cells, precluding the possibility that the differences in complex formation were due to differences in protein expression between TNBC, luminal breast cancer, and mammary epithelial cells." (PMID 29422613, 2018). "Our previous study also did not investigate whether, in addition to NANOG, the expression of other pluripotency factors is regulated by m6A demethylation of mRNA in hypoxic breast cancer cells." (PMID 27590511, 2016). "ER+ PgR+ Ki-67- breast cancer cells were successfully recognized as nuclei with a purple color, indicating that light-field chromogenic triple immunostaining using these chromogens is suitable for use in searching for SOX2+ (or NANOG+) HIF-1α+ RNApII-S2P-/low cells in astrocytoma tissues." (PMID 26799577, 2016). "Based on the inability of NANOG-GFP reporter to enrich CSC in cisplatin-resistant cells, we evaluated other CSC enrichment markers including CD49f, which we and others have previously demonstrated to be an informative CSC marker in brain tumors and breast cancer." (PMID 27105520, 2016). "Predicted regulatory element sequences for NANOG, CREB1, CPBP, BEN, PREB-1, SOX10, and POU2F1 (OCT1) POU6F1 and MEIS1 were highly enriched in the promoter regions of the tissue context dependent genes suggesting their possible roles in stem cells proliferation in HER2-regulated breast cancer tissue." (PMID 25428913, 2015). "We observed that SOX2 and OCT4 expression was significantly increased in tbLCM-treated breast cancer cells as compared to tnLCM or BM treated cells, while expression of SOX9 and NANOG was not different between treatment conditions." (PMID 38581619, 2024). "Cx26 complexed with the pluripotency transcription factor NANOG and focal adhesion kinase (FAK) promotes cancer stem cell self-renewal of TNBC cells but not luminal breast cancer cells." (PMID 37149651, 2023). "Clinically, we found that TAZ and NANOG formed nuclear puncta in ALDH1+ tumor cells in both pre-treatment and post-treatment samples from the chemoresistant breast cancer patients rather than chemosensitive ones." (PMID 36646707, 2023). "Although the mRNA expression of stemness markers, such as SOX2, c-MYC, and NANOG, was reduced by YTHDC2 knockdown, the alteration of gene expression pattern was not the same for all of breast cancer cell lines." (PMID 36245989, 2022). "This complex is specific to TNBC, as NANOG and FAK do not co-immunoprecipitate in mammary epithelial and luminal breast cancer cells." (PMID 29422613, 2018). "In case of breast cancer cell line (MCF7), there was no significant change in OCT4 and NANOG expression upon silencing EpCAM, while SOX2 was downregulated." (PMID 26176230, 2015). "Interestingly, while breast cancer sphere-forming cells showed high SOX2 expression, NANOG and OCT4 were not expressed in these cells, suggesting the presence of heterogeneous CSC populations." (PMID 31137841, 2019). "Interestingly, when we investigated the expression of CSC-related genes in the luminal breast cancer cell line MCF7 without drug treatment, the expression of ALDH1A3, OCT4, and NANOG did not vary as a function of in vitro model." (PMID 28871147, 2017).
breast carcinoma (continued). "Additionally, we found that breast cancer cells that overexpress MEG8 have decreased the expression levels of some stem cell markers such as BMI1, SOX9 and KLF4 and in some cases also NANOG or SOX2, but not OCT4." (PMID 39706842, 2024).